CD4 (CD4 molecule)
Diseases named in the same sentence as CD4 in open-access papers (continued):
Sharing a sentence is not in itself a finding about the gene and the disease.
malnutrition (continued). "It is possible that the increase of BM CD4+ T cells is a consequence of the stress induced by the BM hypoplasia in malnutrition in an attempt to restore the normal hematopoiesis." (PMID 22347448, 2012). "In fact, excellent responses in CD4 count and viral load have been demonstrated among those with severe malnutrition who do receive ART, just as in those with better baseline nutritional status." (PMID 22606378, 2012). "Ľun ďeux ayant une présentation clinique et topographique ďun noma neonatorum observé chez un enfant congolais de 3 ans, VIH séropositif au stade clinique et biologique IV (malnutrition sévère et taux de CD4 à 6%)." (PMID 23308309, 2012). "Even at CD4 counts >25% indicating normal immune status, 33 to 45% of children had moderate to severe malnutrition." (PMID 20041007, 2009). "Our study also highlights the fact that even at relatively early stages of the disease with higher CD4 counts, malnutrition is a substantial problem with over a third of children moderately or severely malnourished." (PMID 20041007, 2009). "During stress, such as that induced by severe malnutrition, the thymus undergoes a severe atrophy due to apoptosis-induced depletion, particularly affecting the immature CD4+ and CD8+ cells, as well as a decrease in cell proliferation." (PMID 19432828, 2009). "The effects of malnutrition on the immune system are well known and include decreases in CD4 Tcells, suppression of delayed hypersensitivity, and abnormal B-cell responses." (PMID 19102765, 2008). "Prolonged malnutrition could impair Cellular Immune Function (CMI), particularly the function of helper T lymphocyte CD4 cells, resulting in increased susceptibility to infections." (PMID 39734673, 2024). "Lower CD4 counts and a high HIV viral load have been linked to severe malnutrition." (PMID 36501001, 2022). "It is plausible that underlying malnutrition was responsible for diminished CD4 + T-cell activity and the absence of granulomatous immune response in these cases." (PMID 35624128, 2022). "Lastly, malnutrition, CD4+ T-lymphocyte count, and ART use were inconsistently collected and could not be included in our model." (PMID 34383824, 2021). "Taken together these results suggest that Moringa supplementation may ameliorate some of the immune suppressive effects induced by malnutrition upon malaria infection such as CD4+ T cell activation." (PMID 32033605, 2020). "Factors that tend to deteriorate the life of patients like malnutrition, OIs, CD4 count below 200 cells/μL, and having suboptimal adherence to ART, ambulatory functional status, being substance abuser and not receiving Isoniazid prophylaxis were significantly associated with LTFU." (PMID 30819236, 2019). "Malnutrition affects both innate and acquired immunity, and the ratio of CD4+/CD8+ T cells." (PMID 29868503, 2018). "The Viral Load Testing Criteria (VLTC) consists of three parameters all independently associated with an increased likelihood of VF: signs of malnutrition (measured by gender-specific MUAC thresholds), CD4 count <350 cells/mm3, and interruption of ART since last visit." (PMID 28914169, 2017). "A possible explanation could be that the association between nutritional status and CD4 counts is influenced by the range of CD4 values or prevalence of malnutrition." (PMID 26825478, 2015). "One study in Uganda has suggested that CD4 counts may differ in oedematous malnutrition, but this needs to be confirmed." (PMID 25475887, 2014). "With assessment of CD4 counts becoming widely available, it has been investigated whether the number of CD4+ lymphocytes was affected by malnutrition." (PMID 25153531, 2014). "As a secondary analysis, we sought to determine whether an association between the Mtb specific CD4+ or CD8+ T response, if associated with time on treatment, might be correlated with malnutrition." (PMID 24324704, 2013).
malnutrition (continued). "Regardless, our finding that the Mtb specific CD4+ T cell response was impacted by malnutrition may account for performance differences in IGRAs when used in low resource/high incidence versus high resource/low incidence settings." (PMID 24324704, 2013). "In spite of the fact that the proportion of malnutrition was higher; (20.5%) among those with severe CD4 cell count and (12.8%) among those in the mild and (9.9%) among those in moderate CD4 cell count category, the association was not statistically significant." (PMID 23759075, 2013). "We also found that prior or current HAART use was statistically associated with higher CD4 cell count and lower viral load, but neither HAART use nor CD4 cell count was associated with malnutrition." (PMID 23144941, 2012). "Marasmic children in one Zambian study showed lower CD4 counts compared to children with edematous malnutrition (kwashiorkor), correlating with the protracted nature of diarrhea observed in these children from opportunistic enteropathogens such as Cryptosporidium." (PMID 22606378, 2012). "If CD4 cell response to ART were lower in malnourished compared to well-nourished individuals, this might imply a causal role of malnutrition in HIV mortality." (PMID 22216334, 2011). "Furthermore, hypoalbuminaemia is a marker of severe malnutrition and was a predictor of low CD4 counts in HIV-negative TB patients." (PMID 20811589, 2011). "Severe malnutrition can also influence CD4 cell values and could have an effect on the predictive value of CD4 cell counts for HIV infection, as 52.1% of our children were severely malnourished." (PMID 19390690, 2009). "Additionally individuals with severe malnutrition had a significant lower CD4 counts in comparison with individuals with normal, mild, or moderate malnutrition." (PMID 19068104, 2008). "With the advent of the human immunodeficiency virus (HIV) pandemic, there has been a tendency to overlook the role of malnutrition in immunodeficiency, and indeed, only a handful of studies have investigated the CD4+ and CD8+ lymphocyte subsets in severely malnourished children." (PMID 17042940, 2006). "In this cohort of African women initiating ART, no measure of malnutrition prior to ART was consistently associated with change in CD4 count at 6, 12, and 24 months of follow up, suggesting that poorer pre-treatment nutritional status does not prevent an excellent response to ART." (PMID 22216334, 2011). "Several risk factors have been consistently identified across studies, including low CD4 count (<200 cells/ul), high viral load (>1000 copies/mL), advanced HIV disease stage, and malnutrition." (PMID 38988810, 2024). "In this regard, the inclusion of specific parameters is of interest, including CD4/CD8 and CD3/CD19 ratios, as these factors are considered as the best immune biomarkers of nutritional status, as they are modulated in situations of malnutrition." (PMID 38201831, 2023). "Malnutrition and HIV play a synergistic role in reducing the number of CD4+ T and CD8+ T cells, delaying skin sensitivity, reducing bactericidal performance, and impairing serum immunological response." (PMID 35003070, 2021). "One must, therefore, question the etiology of the possibly increased CD4/CD8 ratios and intact lymphoproliferative response noted in anorexia nervosa when compared to primary malnutrition." (PMID 31717370, 2019). "On the other hand, malnutrition induces anti-inflammatory cytokines IL-4 and IL-10 and impairs pro-inflammatory cytokines IL-2 and IFN-γ production from CD4+ and CD8+ T cells in children." (PMID 29868503, 2018). "For the investigation of correlations between CD4 cell counts and clinical variables we used both BMI and MUAC as markers for wasting and malnutrition." (PMID 24358268, 2013). "In multivariate analysis, only severe malnutrition (WAZ<−3 SD) and severe immune suppression (CD4<5%) at baseline remained independent predictors of mortality." (PMID 23078768, 2012).
malnutrition (continued). "Malnutrition and HIV infection can deteriorate immune system function including decline in CD4 lymphocyte count and delayed type immune reactions." (PMID 19068104, 2008). "In particular, the CD4/CD8 ratio is seemingly increased in AN compared to primary malnutrition, likely due to a greater reduction in CD8 rather than CD4 cells counts." (PMID 36904132, 2023). "They established that malnutrition had a negative effect on the immune system resulting in a decline of CD4 T-cells, suppression of delayed hypersensitivity and abnormal B-cell responses." (PMID 37042519, 2023). "Besides atypical memory B cells and the exhausted CD4 T cells, the absence of specific antibodies may depend on other factors, such as P. falciparum genetic polymorphisms, intensity of infection, coinfections, malnutrition, or human host genetic factors." (PMID 34983540, 2022). "In the nutritional studies, food limitation induced malnutrition decrease CD4+ T cell activation, but there was no notable difference in pro-inflammatory cytokine production." (PMID 32033605, 2020). "CD4 counts seem to be more greatly decreased than CD8 counts in malnutrition when infection is not present." (PMID 31717370, 2019). "Others have found higher CD4 counts in edematous than non-edematous children with malnutrition, suggesting that these children had better immunity; however, our data does not indicate that this is reflected by a larger thymus." (PMID 28288591, 2017). "While serum albumin is widely used to indicate nutritional status it did not consistently predict malnutrition outcomes in HIV- women or HIV+ women with higher CD4." (PMID 22532840, 2012). "The CD4+ cell percentages were more likely to be below 15% (OR 4.2, CI 1.4–12.6) and between 15%–25% (OR 2.0, CI 0.6 – 6.8) in children with non-oedematous malnutrition than in those with oedema." (PMID 17042940, 2006). "The CD4+ cell percentages in this study were lower in children who presented with non-oedematous severe malnutrition, and this finding was consistent in both HIV-infected and uninfected groups." (PMID 17042940, 2006). "The CD4+ cell percentages were more likely to be lower in children with non-oedematous malnutrition than in those with oedematous malnutrition even after controlling for the HIV infection." (PMID 17042940, 2006). "Nous rapportons ici un cas de CNM chez une patiente VIH-négative atteinte de tuberculose pulmonaire avec une malnutrition, pour mettre en exergue la possibilité de la survenue d'infection opportuniste (IO) chez un patient quels que soient son statut sérologique VIH et son taux de CD4." (PMID 36815177, 2022). "CD4 count below threshold, children aged < 1 year and 1–5 years, baseline malnutrition in the form of severe wasting (WFH < − 3z), not taking cotrimoxazole preventive therapy, and baseline Hgb < 10 gm/dl were significant predictors of mortality among HIV-positive children after initiation of ART." (PMID 35978382, 2022). "In view of the reported high incidence of clinical and/or subclinical infections and malnutrition in low income sub-Saharan populations and the fact that malnutrition further stimulates inflammatory activity, findings of a higher inflammatory activity at comparable CD4 counts comes as no surprise." (PMID 26285873, 2015). "Although we demonstrate a differential effect of malnutrition on the CD4+ T cell response, we suspect that severe protein calorie malnutrition affects both the CD4+ and CD8+ T cell response and we were underpowered to fully assess the effect of malnutrition on the CD8+ T cell response." (PMID 24324704, 2013). "Thus, a low level of CD4+ lymphocytes can probably not be attributed to malnutrition, regardless of whether the child has HIV or not." (PMID 25153531, 2014).
malnutrition (continued). "A possible explanation for the lack of effect seen in severely immunosuppressed patients (CD4 < 100 cells/mm3) may be that ART needs to be established first before malnutrition can be treated or before protein synthesis and immune-related enzyme systems can resume their functions." (PMID 23919622, 2013). "Among patients without malnutrition, in a better WHO clinical stage, CD4+ > 200 and lower VL, 22–24% were anaemic, and 31–40% had some cytopenia." (PMID 33170905, 2020). "Hearing loss was linked to history of WHO Stage 3 (OR 2.4, 1.2–4.5) or Stage 4 (OR 6.4, 2.7–15.2) and history of malnutrition (OR 2.1, 1.3–3.5), but not to duration of ART or CD4." (PMID 27551970, 2016).
Anxiety (104 papers, 2011 to 2026). Intense feelings of nervousness, tension, or panic often arise in response to interpersonal stresses. "The xanthine enters the brain via the bloodstream and directly stimulate the amygdala, causing anxiety-related behaviors, which is primarily caused by mitochondrial fission in CD4+ Tn cells." (PMID 40756310, 2025). "Suicidal ideation is significantly associated with the psychopathology of depressive symptoms, anxiety symptoms, single marital status, CD4 count < 500 cells/μl, and efavirenz use." (PMID 32448151, 2020). "This cross-sectional study aims to explore the role of depressive symptoms and anxiety on the association between food insecurity and CD4 counts among a sample of 2,987 PLWH in Guangxi, China." (PMID 33777501, 2020). "However, in multivariable logistic regression, only occupation, presence of chronic disease, recent CD4 count, anxiety, sleep hygiene, and HIV-related stigma were associated with sleep quality at a P value of 0.05." (PMID 37359994, 2023). "We also analyzed independent covariates from demographic factors, psychopathology, and HIV-related variables; five were found associative to suicidal ideation—depressive symptoms, anxiety symptoms, single marital status, latest CD4 count of less than 500 cells/μl, and efavirenz use." (PMID 32448151, 2020). "In this study, patients expressed several practical benefits of same-day POC CD4 testing: It would save time and days off work, cause less anxiety, and be a cost saver, which have been found to be important factors resulting in loss of linkage to care if not addressed." (PMID 32024166, 2020). "Being a farmer, being a merchant, having chronic diseases, having anxiety, having a CD4 count of 200–499 cells/mm3, being stigmatized, and having poor sleep hygiene were factors that had an association with poor sleep quality." (PMID 37359994, 2023). "Depletion of CD4 + cells decreases the anxiety-like behavior of mice subjected to the endometriosis model, whereas abdomino-pelvic hypersensitivity, depressive-like behavior and cognitive deficits remain unaltered." (PMID 36311856, 2022). "What's more, evidence shows that defects of immune cells, including CD4+ T‐cells, Th17/Treg, mast cell and microglia, lead to mouse anxiety or anxiety‐like behaviours." (PMID 35854653, 2022). "Most studies on the adaptive immune role in anxiety have examined the presence of CD4 + (T helper) and CD8 + (cytotoxic) T lymphocytes, immune cells known to be involved in the pathogenesis of MS." (PMID 35092543, 2022). "Peripheral xanthine derived from CD4+ T cells was shown to act in amygdala and thereby to induce anxiety, similar to the present concepts." (PMID 36045177, 2022). "Defects of immune cells, including CD4+ T‐cells, Th17/Treg, mast cell and microglia, lead to anxiety or anxiety‐like behaviours." (PMID 35854653, 2022). "The present data reveal the involvement of the immune response characterized by CD4 + white blood cells in the anxiety-like behavior induced by endometriosis in mice." (PMID 36311856, 2022). "The involvement of lymphocytes in MDD is paralleled by previous data showing that anxiety in mice upon application of electronic foot shocks is mediated by an increased synthesis of purines in CD4+ T cells." (PMID 36045177, 2022). "The development indirectly supplements the results of previous studies, that is, like anxiety mice, CD4+ T cells also play an equally important role." (PMID 34955935, 2021). "A study on cell research implicated an important link between purine metabolic dysfunction in CD4+ T cells and anxiety-like behaviors." (PMID 34646171, 2021). "A comprehensive and exhaustive study in a mouse model has been performed, showing that CD4+ T cells are essential for the onset and development of stress-induced anxiety behaviors." (PMID 32054062, 2020).